LPL (lipoprotein lipase)
Diseases named in the same sentence as LPL in open-access papers (continued):
Sharing a sentence is not in itself a finding about the gene and the disease.
Obesity (continued). "Obesity is, however, not only related to an increase in the contribution of FA to the liver for the production of TG but also affects the clearance of these particles as it is associated with an increase in apolipoprotein CIII levels, an LPL inhibitor." (PMID 36077235, 2022). "Our data demonstrated that RSE could significantly ameliorate obesity characteristics of HFD-fed mice by regulating tissue specific lipoprotein lipase (LPL) activities." (PMID 35885328, 2022). "Moreover, extract of fermented Curcuma longa L., which is rich in curcuminoids, prevented obesity by inducing a statistically significant decrease in the mRNA expressions of LPL in the white adipose tissue of obese mice." (PMID 35885328, 2022). "Moreover, studies suggest both obesity and alcohol intake affect the process of lipoprotein lipase (LPL) generation, which plays an important role in the pathogenesis of dyslipidemia." (PMID 34948819, 2021). "Eggplant may have shown protective effects on hyperlipidemia and obesity via the induction of lipoprotein lipase activity and the reduction of pancreatic lipase activity.Eggplant can be useful in the treatment of MetS and its complications." (PMID 34094022, 2021). "Interestingly, we found that, despite obesity, mice with reduced neuronal LPL showed improved glucose tolerance with aging, a phenotype that involves reduced hepatic EGP and preserved hepatic insulin sensitivity despite aging and obesity." (PMID 32998280, 2020). "Between the muscle and adipose tissues the partitioning of plasma TG disrupted due to the inequities in LPL activity and their availability, this may also lead to and obesity and insulin resistance." (PMID 32847584, 2020). "Moreover, astrocyte-specific depletion of LPL in vivo, exacerbates high-fat diet-induced obesity, suggesting that astrocyte-derived LPL is involved in central homeostasis and peripheral metabolism." (PMID 33172164, 2020). "Moreover, lipoprotein lipase (LPL) activity in adipose tissue has been suggested to be closely related to obesity formation." (PMID 31540318, 2019). "For instance, dysbiosis may affect lipid metabolism and trafficking in both liver and adipose tissue by upregulating lipogenic enzymes or lipoprotein lipase (LPL) thus participating to obesity and steatosis development." (PMID 31689910, 2019). "Altogether, our data clearly reveal sex differences in hepatic PL and LPL composition, suggesting a sex-specific regulation of PL synthesis in mouse liver that may contribute to the sexual dimorphism observed during obesity." (PMID 30808418, 2019). "The resulting increased LPL corresponds to a microbiota-mediated increase in fat storage that may be part of the sex difference in body composition and obesity." (PMID 31182162, 2019). "Ageing, obesity, diet, drugs, hyperinsulinaemia, exercise and other factors may promote clinical manifestations of LPL-gene heterozygous defects." (PMID 29921298, 2018). "The expression of hHL also promoted obesity and upregulated the adipose LPL-mediated FFA influx." (PMID 29244870, 2017). "Previous data suggested that lpl expression and activity in obese subjects are downregulated in an insulin-resistant compared to an insulin-sensitive state, and that an increase of lipoprotein lipase in adipocytes improves glucose metabolism in HFD-induced obesity." (PMID 28327129, 2017). "The interaction between body mass index (BMI) and the LPL genotype may explain the deleterious role of obesity on lipid profile levels." (PMID 26786614, 2016). "Since insulin levels and activity are related to body weight, it can be hypothesized that LPL activity is affected by obesity." (PMID 26786614, 2016).
Obesity (continued). "Studies indicate that an imbalance in the activities of the glucose transporter GLUT4 and lipoprotein lipase between muscle and adipose tissue may be important in the development of obesity." (PMID 26927389, 2016). "Potential obesity and T2D-related genetic variants that may influence athletic performance as well are located in the IGF2BP2, LPL, KCJN, and MTHFR genes." (PMID 25612568, 2015). "We recently created neuron-specific LPL deficient mice (NEXLPL-/-) that develop obesity by 16 wks on standard chow, and display marked reductions in omega-3 polyunsaturated fatty acids in the hypothalamus at 3 months, before the onset of obesity." (PMID 26263173, 2015). "We studied the association between five obesity and co-morbidities-related genetic variants (IGF2BP2 rs4402960, LPL rs320, LPL rs328, KCJN rs5219, and MTHFR rs1801133) and athletic status in a well-defined (athletic level, ethnicity, gender) athletic population." (PMID 25612568, 2015). "Vitamin D may decrease serum TG through a regulatory action that increases the activity of lipoprotein lipase in persons with obesity." (PMID 25371907, 2014). "Considering that LPL activity has impact on obesity and metabolic syndrome, its targeting may also affect the regulation of adipocytokines, which may also be involved in carcinogenesis." (PMID 22028972, 2012). "Moreover, recent evidence that LPL plays important roles in inflammation and obesity implies that it is an appropriate general target for chemopreventive and chemotherapeutic agents." (PMID 22028972, 2012). "ESR-1, LPL, and APO E genetic polymorphic variants could represent predictive genetic risk markers for obesity-related metabolic disorders in young healthy subjects." (PMID 19804633, 2009). "An inhibitory action of estrogens on lipoprotein lipase has been described to explain the inhibition of obesity development by estrogen replacement therapy in rats; however, we do not have any evidence that support a similar action for the inhibitory effect of OE treatment." (PMID 17725831, 2007). "In the study of diet-induced obesity, it was confirmed that macrophages in adipose tissue metabolically activate FFAs released by the lipolysis of triglycerides from adipocytes or triglyceride-rich lipoproteins by lipoprotein lipase involving the Cd36 receptor." (PMID 40299533, 2025). "The anti-obesity properties of resveratrol may be connected to its anti-diabetic properties, with decreased action of lipogenic enzymes (acetyl-CoA carboxylase, glucose-6-P-dehydrogenase, and lipoprotein liPase)." (PMID 37241737, 2023). "Another enzyme is lipoprotein lipase, it hydrolyzes triglycerides in the blood to release free fatty acids and so enhances triglyceride storage in adipose tissues, and its inhibition lowers the accumulation and assimilation of free fatty acids and hence controls obesity." (PMID 38455221, 2023). "Also, the LPL SX genotype had a protective role against obesity." (PMID 36605456, 2023). "Herein, we investigated whether the anti-obesity effect of RSE is due to LPL activity regulation." (PMID 35885328, 2022). "Conversely, higher LPL describes a condition of increased lipid storage in adipocytes, which may serve as a protective mechanism against ectopic fat distribution and related metabolic disease in obesity." (PMID 33003532, 2020). "Conversely, higher LPL expression describes a condition of increased lipid storage in adipocytes, which may serve as a protective mechanism against ectopic fat accumulation and related metabolic disease in obesity." (PMID 33003532, 2020). "For lipid- and non-lipid-associated obesity as a therapy associated to non-specific anti-obesity drugs the specific LPL activators may substantiate much valuable with respect to skeletal muscle or tissues." (PMID 32847584, 2020). "In addition, apoCI transgenic mice present lower LPL activity and are protected against obesity." (PMID 26705406, 2015).
Obesity (continued). "Acylation stimulating protein (ASP) is a circulating adipokine elevated in obesity, diabetes and cardiovascular disease as well as other metabolic disorders with hyperlipidemia such as polycystic ovarian syndrome (PCOS), hypothyroidism and lipoprotein lipase (LPL) deficiency." (PMID 20416070, 2010). "Moreover, the patients with hypertriglyceridaemic pancreatitis without LPL deficiency were more likely to have associations with important environmental factors, such as diabetes, obesity and alcohol consumption." (PMID 19534808, 2009). "Firstly, we detected expression levels of key adipogenesis genes, such as CEBPA, PPARG, lipoprotein lipase (LPL), fatty acid binding protein 4(FABP4) and perilipin 1 (PLIN1), which play critical roles in the development of obesity." (PMID 39773638, 2025). "G. pentaphyllum has demonstrated anti-obesity effects through the activation of the AMPK–SIRT1 pathway, the enhancement of lipoprotein lipase activity, the promotion of fatty acid oxidation, and the inhibition of lipogenesis." (PMID 41011571, 2025). "In the context of obesity, the apolipoprotein C-II (Apo C-II) present on the VLDL surface activates lipoprotein lipase, promoting the hydrolysis of triglycerides." (PMID 41458553, 2025). "In mice with high-fat diet-induced obesity, administering 12,13-diHOME promoted fatty acid transport into BAT, reduced circulating triglyceride levels, and increased LPL gene expression, facilitating triglyceride hydrolysis." (PMID 40183584, 2025). "This analysis showed that some proteins, such as COL1A1, COL6A3, FABP4, LEP, LGALS1, and THBS4, are obesity-specific, and GDF15, LPL, MCFD2, REG1A, REG1B, and TCN2 are T2D-specific." (PMID 38732002, 2024). "However, the molecular mechanisms mediating LPL during obesity are largely unknown." (PMID 38973609, 2024). "We found that LPL polymorphism rs328 is not characterized by the differences in the levels of hormones, adipokines, and myokines and in the blood of healthy children and adolescents; however, it significantly affects these indices during obesity in gender-dependent manner." (PMID 37901192, 2023). "Using this approach, we detected rs11863726 in hemoglobin subunit theta 1 (HBQ1), rs328 in lipoprotein lipase (LPL), and rs112984085 in Vav guanine nucleotide exchange factor 3 (VAV3) for T2D and obesity." (PMID 37623486, 2023). "Therefore, if skeletal muscle-specific LPL activity is increased, or adipose tissue-specific LPL activity is decreased, it may be able to reduce fat accumulation and increase energy expenditure, achieving the purpose of anti-obesity." (PMID 35885328, 2022). "Specifically, VW extract suppressed obesity by downregulating PPAR-γ and its target genes (LPL, CD36, HMGCR, and L-FABP), thereby disrupting adipogenesis and lipid accumulation." (PMID 36193302, 2022). "Lipid transport protein expressions, e.g. lipoprotein lipase (LPL) and fatty acid binding protein 4 (FABP4), are altered in human obesity." (PMID 32321549, 2020). "With respect to lipid metabolism we expected a down-regulation in LPL and FABP4 expression in AT with increasing obesity." (PMID 32321549, 2020). "In the physiology of obesity, increased FFAs stimulate ANGPTL4 secretion which inhibits LPL activity to reduce lipid loading." (PMID 32641980, 2020). "Our findings provide insights into the understanding of ANGPTL4 and LPL pathways in human adipose tissue and add knowledge on ANGPTL4 involvement in glucose regulation in obesity." (PMID 33003532, 2020). "During obesity, the response of lipoprotein lipase activity to glucose stimulation has been shown to be reduced, representing one potential factor contributing to the decrease of HDL-C in obesity." (PMID 33256096, 2020). "The levels of the LPL and FABP1 mRNAs in the liver were determined to elucidate the role of hepatic fat metabolism in obesity." (PMID 31211018, 2019).
Obesity (continued). "SCFAs also act on obesity development via suppression of the fasting-induced adipocyte factor (FIAF)/angiopoietin-like protein, an important inhibitor of lipoprotein lipase (LPL), as demonstrated in mice gut microbiota." (PMID 31182162, 2019). "The intervention also accentuated the obesity‐induced induction of SREBP and LPL in the maternal WAT, compared to the lean control group." (PMID 31466137, 2019). "Decreased LPL activity mitigates degradation and clearance of TG-rich VLDL resulting in increased TG and decreased HDL-C levels in plasma, hyperlipidemia, and obesity." (PMID 31450828, 2019). "Regarding lipid metabolism, some studies have shown that AH has pronounced effects on obesity by down-regulating GLUT-4 in adipocytes and hepatic mRNA levels of FAS and LPL in diet-induced obese mice." (PMID 31547031, 2019). "As both ANGPTL3 and ANGPTL4 are important in lipid metabolism through their interaction with lipoprotein lipase, our data suggest a role for ANGPTL5 in TGL metabolism in obesity." (PMID 31396158, 2019). "Obesity increases free fatty acid (FFA) fluxes to the liver, adipose tissue, and skeletal muscle, which leads to alter expression of lipoprotein lipase (LPL) activity and hampers lipolysis and TG accumulation and transport, subsequently causes dyslipidemia." (PMID 28883832, 2017). "The target genes regulated by PPARα and involved in lipid metabolism and obesity include CD36, LPL, ACC, ABCA1, CYP4a10, CYP4a14, UCP2, ACO and SCD1." (PMID 24705395, 2014). "Co-localization analysis suggested that LPL (as a TG-lowering drug target), CETP (as an HDL-raising drug target), ABCC8 (as a glucose-lowering drug target) and GIPR (as an anti-obesity drug target) were unlikely to share a causal variant with LS." (PMID 39661645, 2025). "Additionally, we observed the potential beneficial effects of CCB-targeted drugs on cSVD imaging markers and of CETP-targeted, LPL-targeted and GIPR obesity-targeted drugs on LS." (PMID 39661645, 2025). "In addition, Blautia has complex effects on lipid metabolism; it is positively correlated with obesity-promoting indicators such as DGAT and ALT but also positively correlated with obesity-preventing indicators such as LPL and PPAR-α." (PMID 38999751, 2024). "We aimed to assess the DNA methylation levels in the promoters of MC4R and LPL genes from maternal blood, placenta, and buccal swab samples collected in children born to mothers with and without obesity and Gestational Diabetes Mellitus (GDM)." (PMID 39458497, 2024). "Probiotics containing Lactobacillus paracasei can impact adipose tissue mass by modulating the activity of angiopoietin-like protein 4, a circulating lipoprotein lipase (LPL) inhibitor that controls TG deposition into adipocytes, which can help prevent obesity and metabolic disorders." (PMID 35897822, 2022). "Therefore, this study was designed to explore the anti-obesity effects of RSE from lotus seed on high-fat diet-fed mice and determine the anti-obesity properties through regulating the LPL activity in vivo." (PMID 35885328, 2022). "In addition, obesity-induced dysbiosis decreases the expression of fasting inducing adipose factor (FIAF), thus increasing the activity of lipoprotein lipase (LPL) that facilitates the transport and thus the storage of fatty acids by peripheral tissues." (PMID 35267899, 2022). "In addition, the high expression level of CD36 and LPL in N + samples further verified the importance of an exogenous supply of lipids in LNM, reflecting the impact of obesity on nodal metastasis in another way." (PMID 36397145, 2022). "Among those genes are insulin receptors, fatty acid synthase, lipoprotein lipase, adiponectin, leptin, acetyl-CoA carboxylase beta, and fatty acid binding protein 4 (FABP4), the latter being a new player connecting obesity with breast cancer development." (PMID 33801973, 2021).
Obesity (continued). "Butyrate has anti-obesity effects through upstream regulation of the expression of angiopoietin-like protein-4 (ANGPTL4) in human epithelial cells, resulting in the reduced expression of lipoprotein lipase (LPL) and increased lipolysis." (PMID 32668581, 2020). "By means of lipoprotein lipase (LPL) these different fats are hydrolyzed into FFA that are taken by the adipose tissue cells, re-esterified into TG and stored as lipid droplets leading to obesity." (PMID 32616730, 2020). "Though, there was no alteration in fat accumulation quantity of which showed that obesity was not brought due to advanced LPL activity." (PMID 32847584, 2020). "Therefore, this study aimed to investigate ANGPTL4 and LPL expression in visceral AT (VAT) in relation to (i) local inflammation and dysfunction and (ii) clinical alterations, in human obesity." (PMID 33003532, 2020). "The selected features of the proposed classifier on the Set 1 were CETP TaqIB [rs708272], CETP A373P [rs5880], LPL D9N [rs1801177], ApoE, ABCAI R1587K [rs2230808], APOA5 C-1131T [rs662799], LPL HindIII [rs320], APOC3 SstI [rs5128], family history of obesity, and diabetes, and APOA1 MspI [rs2893157]." (PMID 30026888, 2018). "On the contrary, we show here and elsewhere that apoCIII overexpression does not change plasma LPL activities and still results in diet induced obesity." (PMID 26705406, 2015). "In addition to higher amount of TG along with lipoprotein lipase (LPL) activity within WAT, obesity prone-rats from cafeteria-diet-fed dams throughout gestation and lactation exhibited modified fatty acid composition." (PMID 26029119, 2015). "The associations of 23 SNPs located within 17 candidate genes (MTHFR, PPARγ, LPL, INSIG, TCF7L2, FTO, KCNJ11, JAZF1, CDKN2A/B, ADIPOQ, WFS1, CDKAL1, IGF2BP2, KCNQ1, MTNR1B, IRS1, ACE) with overweight and obesity, diabetes, metabolic phenotypes, and MetS were examined in both studies." (PMID 24959828, 2014). "In this study, we simultaneously confirmed that the anti-obesity abilities of DOW-RMD in inhibiting PPARγ and C/EBPα expression in differentiation and lipoprotein lipase activity in lipogenesis were contributed to by the DOW-increased monascin and ankaflavin levels and the ions of DOW, respectively." (PMID 24132179, 2013). "In the cell test, the anti-obesity abilities of DOW-RMD in inhibiting PPARγ and C/EBPα expression in differentiation and lipoprotein lipase activity in lipogenesis were contributed to by the DOW-increased monascin and ankaflavin levels and the ions of DOW, respectively." (PMID 24132179, 2013). "Since LPL catalyzes the hydrolysis of blood triglycerides to release free fatty acids (FFA) and hence increases the storage of triglycerides in adipose tissue, inhibition of LPL is expected to reduce assimilation of FFA and help in controlling obesity." (PMID 22666121, 2012). "This study shows that the obesity-resistant phenotype of CB1-deficient mice is not due to changes in adipose tissue differentiation and -proliferation, lipogenesis or LPL-activity in vivo." (PMID 22201701, 2011). "Lipoprotein lipase (LPL) is the key enzyme for the hydrolysis of circulating triglycerides (in chilomicra and VLDL lipoproteins) into free fatty acids and glycerol and plays a major role in adipocyte lipid storage and hence the regulation of obesity." (PMID 17725831, 2007). "Finally, modulation of FIAF can further support obesity management by promoting bacteria like A. muciniphila, Lactobacillus spp., and Bifidobacterium spp., which upregulate FIAF to inhibit LPL activity and reduce fat storage, fostering a leaner body composition." (PMID 40183584, 2025). "Active compounds such as 6-gingerol decreased obesity by changing the activities and expression levels of some lipid metabolism markers, such as FAS, ACC, 3-hydroxy-3-methylglutaryl-CoA reductase (HMGCR), lecithin choline acyl transferase (LCAT), and lipoprotein lipase (LPL)." (PMID 37050926, 2023).